CX3CL1 (C-X3-C motif chemokine ligand 1)
Diseases named in the same sentence as CX3CL1 in open-access papers (continued):
Sharing a sentence is not in itself a finding about the gene and the disease.
tumor (continued). "The combination treatment caused increased secretion of CCL2, CCL21, CXCL1, CXCL2, CXCL5, CXCL9 and CXCL16, whereas the levels of CCL11, CCL17, CCL19, CCL22, CCL25, CCL27 and CX3CL1, which are associated with protumourigenic effects, were decreased in the tumours." (PMID 33014356, 2020). "Likewise, a cluster containing CX3CL1 and complement inhibition also associated with tumor progression (p=0.04) and inversely with the adenosine signature." (PMID 30400835, 2018). "Thus, GILZ overexpression is clearly associated with higher levels of CX3CL1 production in tumors, resulting in higher rates of proliferation and tumor growth." (PMID 21750716, 2011). "Along with tumor-associated macrophages (TAMs), microglia largely contribute to immunosuppression through the interaction and synergistic release of soluble factors such as granulocyte-macrophage colony-stimulating factor (GM-CSF), C-X3-C Motif Chemokine Ligand 1, (CX3CL1), and SDF1." (PMID 34571905, 2021). "Further studies are clearly required to fully understand whether CX3CL1 expression may help define patient risk and aid in distinguishing between susceptibility to molecular tumor subtypes during early cancer development before histological abnormalities are detected." (PMID 23029290, 2012). "Further analysis of chemokine communication revealed that CXCL14 and CX3CL1, secreted by MBT tumor cells, recruited macrophages through the CXCL14_CXCR4 and CX3CL1_CX3CR1 axes." (PMID 41322338, 2026). "Taken together, these findings indicated that CX3CL1 enhanced the function of Treg cells to suppress anti‐tumor immunity." (PMID 39783838, 2025). "After finalization due to reached endpoints, Cx3cl1 mRNA expression in mesenteric tumour tissue was still significantly higher in the Cx3cl1 overexpressing group (2.64 vs. 1.97 2^-ΔCt, P = 0.038)." (PMID 39862711, 2025). "Given the observed correlation between CX3CL1 expression in tumor samples and patient survival, we expanded our sample size to examine this relationship in HCC patients receiving interventional therapy." (PMID 40051011, 2025). "In our study, the presence of CX3CR1+ MDSCs in the tumor microenvironment, likely driven by CX3CL1, appeared to contribute to this immunosuppression, potentially facilitating tumor progression." (PMID 40051011, 2025). "As the CX3CL1 chemokine is expected to promote the recruitment of T-cells, natural killer cells and monocytes to the tumour microenvironment, we conducted immunohistochemical stainings of immune cell subsets." (PMID 39862711, 2025). "It is likely that the PARP inhibitor-mediated activation of the cGAS/STING pathway is responsible for this CX3CL1 induction, as it has also been found in BRCA-deficient tumour cells, causing similar STING activation as PARP inhibitors." (PMID 39862711, 2025). "In summary, our findings establish the IL26 and CX3CL1 signaling as a critical mediator of BM-CAF-induced tumor progression and therapy resistance in NSCLC BM, suggesting a potential therapeutic strategy for this challenging disease." (PMID 41029793, 2025). "Elevated CX3CL1 levels were significantly correlated with increased MDSC infiltration in the tumor microenvironment and poorer patient prognosis." (PMID 40051011, 2025). "CD8-positive cytotoxic T-cells were approximately 1.6-fold more abundant in Cx3cl1+ tumours (P = 0.029)." (PMID 39862711, 2025). "In summary, our study highlights the potential role of CX3CL1 in shaping the tumor microenvironment by recruiting MDSCs and possibly contributing to immune evasion in HCC." (PMID 40051011, 2025). "Functionally, plasmacytoid DCs that produce IFNα stimulate the recruitment of CX3CR1+ MDSCs through hepatocyte IRF1/CX3CL1 signaling, resulting in tumor recurrence after hepatectomy in HCC." (PMID 40470380, 2025). "Future studies focused on the CX3CL1‒CX3CR1 axis in the tumor microenvironment, including blockade experiments, are needed to validate these mechanisms." (PMID 40051011, 2025).
tumor (continued). "Fractalkine/CX3CL1 is also a myokine which regulates tumor microenvironments by inducing anti-tumor immunity in a mouse model of HCC." (PMID 40136677, 2025). "Accordingly, it has been reported that an increased expression of CX3CL1 sustained anti-tumor responses by favoring the infiltration of NK cells, T-cells, and dendritic cells into the tumor." (PMID 40362536, 2025). "The chemokine CX3CL1 recruits tumour-suppressive T-cells into solid tumours, but also mediates cell–cell adhesions, e.g. of tumour cells, through its membrane-bound form." (PMID 39862711, 2025). "While the top three KLF4-assocaited genes correlated with a tumor stimulatory effect for several tumors were CX3CL1, TNFRSF4, and IL1A." (PMID 40299916, 2025). "In terms of function, plasmacytoid DCs that produce IFNα stimulate the recruitment of CX3CR1+ MDSCs through hepatocyte IRF1/CX3CL1 signaling, subsequently promoting tumor recurrence following hepatectomy in HCC." (PMID 40470380, 2025). "The fact that the promoting effect of CX3CL1 on tumour growth was completely reversed in the s.c. model despite comparable CX3CL1 overexpression further supports the special role of the peritoneal milieu." (PMID 39862711, 2025). "An increase in the expression of CX3CL1 will lead to an increase in the anti-tumor immune response, thereby reducing the rate of tumor growth and improving the survival rate of experimental animals and cancer patients." (PMID 41169393, 2025). "This indeed seems to be a peculiarity of the intraperitoneal milieu, as CX3CL1 overexpression in subcutaneous tumour implantation of the same cell line resulted in successful tumour suppression, which was most likely immune-mediated." (PMID 39862711, 2025). "By understanding the role of CX3CL1 in immune escape and tumor immune modulation, new targeted therapeutic strategies have been developed." (PMID 41376630, 2025). "On the other hand, there are reports that CX3CL1 acts as a tumor suppressor and is involved in the development of ccRCC." (PMID 40508161, 2025). "IL-15Rα+ve TAMs lowered CX3CL1 protein levels in tumor cells, inhibiting CD8+ve T cell recruitment via secretion of the IL-15/IL-15Rα complex (IL-15Rc)." (PMID 39858015, 2025). "In an in vivo study, CAR-T cells expressing CX3CR1 demonstrated enhanced migration towards tumor cells producing CX3CL1, leading to tumor regression." (PMID 41200177, 2025). "Intratumoral recombinant CX3CL1 (rCX3CL1) administered with ICT at ZT18 reduced tumor volume and improved survival to levels comparable to ZT2 ICT treatment." (PMID 41279119, 2025). "In MOC1 tumors, the increase of CX3CL1 led to a smaller tumor size and increased tumor keratinization, indicating its potential anti-tumor effect." (PMID 41445742, 2025). "To further explore the mechanisms by which CX3CL1 influences the tumor microenvironment, we conducted qPCR and ELISAs." (PMID 40051011, 2025). "The results showed that the high‐CX3CL1‐expression group had a significantly greater infiltration level of Tregs and lower T‐cell effectiveness (steps 5–7) in tumor tissue than did the low‐expression group." (PMID 39783838, 2025). "Conversely, IL-15RαTAMs can reduce the protein level of the chemokine CX3CL1 in tumor cells by releasing the IL-15/IL-15Rα complex (IL-15Rc), inhibiting the recruitment of CD8+T cells." (PMID 41445742, 2025). "In the s.c. model, where we were able to blank the peritoneal environment out, we assume that CX3CL1-mediated immune activation slows tumour growth, as we and others have been able to show in other tumour models in vivo." (PMID 39862711, 2025). "In GC, through increased recruitment of immune cells such as effector T cells and NK cells, CX3CL1 enhances the anti-tumor immune response and limits tumor growth and metastasis." (PMID 41376630, 2025).
tumor (continued). "And yet, CX3CL1 overexpression accelerated intraperitoneal tumour growth and shortened survival in vivo." (PMID 39862711, 2025). "Meanwhile, the YUMM1.7 model was more sensitive to chemotherapeutic treatment, secreted higher levels of chemokines CCL2, CXCL1, and CX3CL1, and showed higher infiltration of lymphocyte and myeloid subsets at the same tumor size." (PMID 40878826, 2025). "Tumor-associated macrophages (TAMs), comprising up to 50% of the tumor mass, are recruited via chemokine axes such as CCL2/CCR2, CX3CL1/CX3CR1, and CXCL12/CXCR4 and adopt an M2-like immunosuppressive phenotype, facilitating immune escape and angiogenesis." (PMID 41002423, 2025). "CX3CL1 expression in HCC tumor tissues was assessed via immunohistochemistry, while plasma levels were quantified using enzyme-linked immunosorbent assays (ELISAs)." (PMID 40051011, 2025). "Our studies show that the influence of CX3CL1 on tumour growth is highly dependent on the surrounding milieu." (PMID 39862711, 2025). "HCC cell‐derived CX3CL1 facilitates platelet infiltration into the tumor and subsequently triggers apoptosis of HCC cells." (PMID 40145607, 2025). "Patients with CX3CL1 overexpressing tumours showed a significantly shorter progression-free survival (PFS) than the low-expressing group (median 15.5 vs. 20 months; HR 1.44, 95% CI 1.04-2.00; P = 0.026)." (PMID 39862711, 2025). "Neurons and tumor cells express CX3CL1, which interacts with CX3CR1 on microglia, promoting tumor cell invasion and microenvironment modulation." (PMID 41002423, 2025). "CX3CL1 is recognized for its role in attracting cytotoxic T cells and natural killer cells, which are crucial for anti-tumor immunity." (PMID 40458414, 2025). "The CX3CL1/CX3CR1 axis has emerged as a key player in the tumor microenvironment of various hematologic malignancies." (PMID 40508161, 2025). "Co-expression of CX3CL1 and CX3CR1 by tumor cells was significantly associated with longer disease-free and disease-specific survival." (PMID 40508161, 2025). "We observed increased colocalization of CX3CR1+ cells and PDPN+ structures with increasing lymph-circulating tumor cells after CX3CL1 overexpression." (PMID 38775151, 2024). "On the other hand, CX3C motif ligand 1 (CX3CL1) is a double-faced chemokine with anti- and pro-tumor functions." (PMID 38775151, 2024). "To check the tissue expression of CX3CL1 in the TME, we immunostained and counted CX3CL1+ cells in the primary tumor tissues of MOC1 and MOC2." (PMID 38775151, 2024). "CX3CL1 was expressed in tumor cells, pericytes, and prominently in endothelial cells, while having negligible expression in immune cells (myeloid cells and T and B lymphocytes)." (PMID 39272976, 2024). "It is conceivable that the supplementary CX3CL1 introduced alongside the already secreted CX3CL1 by the MTX-treated tumour cells resulted in an excessively high concentration of CX3CL1, which ceases to elicit an additive effect." (PMID 39011040, 2024). "Previous study observed that CX3CR1 ectopic expression improved the recruitment of adoptively transferred T cells toward CX3CL1-generated cancers, leading to the augmentation of T-cell infiltration and reduction of tumor growth." (PMID 39290304, 2024). "Intriguingly, NR4A1-dependent LY6Clo NCMs migrate toward tumor colonies using the CX3CR1/CX3CL1 axis, where they have been suggested to mediate tumor lysis." (PMID 39545417, 2024). "The primary tumor tissues were then immunostained and counted to confirm CX3CL1 overexpression in vivo." (PMID 38775151, 2024).
tumor (continued). "It is therefore worth noting that anti-inflammatory chemokines including CSF1, CD276, VEGFA, and CX3CL1 were upregulated in pedB tumor epithelial cells." (PMID 39482394, 2024). "The CX3CL1/CX3CR1 axis has an anti-tumor effect by acting as a chemotactic cytokine recruiting immune cells such as NK and T cells, but the complex can also activate pro-tumoral responses." (PMID 39594776, 2024). "We also observed that tumor sizes become significantly smaller when chemokine domain was removed from CX3CL1." (PMID 38775151, 2024). "CX3CL1 also plays a role in the recruitment and activation of immune cells within the tumor microenvironment." (PMID 38456941, 2024). "CX3CL1 is another important chemoattractant recruiting immune cells toward tumor tissue and has been found to be a positive prognostic factor in numerous cancers, including BC." (PMID 38742103, 2024). "In gastric cancer research, lactate, through its interaction with the receptor GPR81, upregulates the expression of CX3CL1, promoting the migration of regulatory T cells (Tregs) to the tumor microenvironment, thereby enhancing the tumor’s immune resistance." (PMID 39654883, 2024). "MOC2Δcd-CX3CL1 tumors showed a significant reduction in tumor sizes compared with MOC2CX3CL1 tumors." (PMID 38775151, 2024). "Overall, these data support the model of Vhl deficiency–driven upregulation of the CX3CL1/CX3CR1 axis engagement as a mechanism that leads to increased myeloid infiltration and a distinct tumor-promoting inflammatory TAM state in the TME of RCC." (PMID 38618956, 2024). "Of note, the therapeutic effect of CX3CL1 during MTX treatment in MCA205 tumour-bearing mice decreased the tumour size but this decrease was not statistically significant." (PMID 39011040, 2024). "The potential mechanism by which CX3CR1 influences CD14+ CD16− monocytes to facilitate the progression of PCa is through activation of the CX3CR1/CX3CL1 signalling pathway, promoting tumour angiogenesis, migration, and invasion." (PMID 39098992, 2024). "On the contrary, injection of dendritic cells engineered to express CX3CL1 to tumor-bearing mice led to accumulation of antitumoral T cells in the tumor milieu and suppression of tumor growth." (PMID 38786066, 2024). "Amanda’s study showed that ITGAL promotes Cx3cr1 expression, cx3cl1-mediated migration and Ccl5 expression in microglia, thereby promoting microglial infiltration and tumor formation." (PMID 39605903, 2024). "In colorectal cancer, elevated tumor expression of CX3CL1 has been correlated with improved prognosis and increased infiltration of CX3CR1-expressing cytotoxic NK and T cells." (PMID 39409924, 2024). "Our study revealed that when aggressive cancer cells gain high CX3CL1 expression, they can alter the vessel architecture of the primary tumor." (PMID 38775151, 2024). "Accumulation of tumor-infiltrating MDSCs including both G-MDSCs and M-MDSCs can also be regulated by chemokine CX3CL1 in HCC, which is upregulated by adoptive transfer of cytokine-induced killer (CIK) cells, a mixture of immune cells." (PMID 38397901, 2024). "Subsequent analysis using TCGA database highlighted a significant correlation between CX3CL1 expression in tumor tissues and patient prognoses." (PMID 39262781, 2024). "The fractalkine axis (CX3CL1/CX3CR1) is a key factor in the interaction between tumor cells and growth-supporting cells in the TME." (PMID 39594776, 2024). "Our study revealed that MSC recruits CX3CR1high macrophages and promotes M1 polarization to inhibit tumor growth via highly secretion of CX3CL1.The combination of MSC and αPD1 was superior to monotherapy against CRC." (PMID 36843945, 2023). "Overexpressed CX3CL1 promotes several cellular responses related to cancer metastasis, including cell movement, migration and invasion in tumour cells." (PMID 37082943, 2023).
tumor (continued). "According to a number of studies, CX3CL1 plays a critical role in fostering robust anti-tumor activity by recruiting NK cells and T cells into the tumor microenvironment." (PMID 37153002, 2023). "CAAs increase the levels of CCL2 to recruit TAMs, which release the IL-15/IL-15 receptor complex to reduce C-X3-C motif chemokine ligand 1 (CX3CL1) expression in tumor cells." (PMID 36765683, 2023). "To test this, we pre-treated CT26 tumor cells with 10 μg/ml of the CX3CR1 mAb followed by addition of CX3CL1 recombinant protein." (PMID 37771579, 2023). "On the other hand, the CCL28, CXCL14 and CX3CL1 expression levels were higher than those in other tumours." (PMID 37484803, 2023). "One important factor is CX3CL1 as myeloid cells have been shown to have high expression of CX3CR1 and traffic towards a CX3CL1 gradient found in the tumor microenvironment." (PMID 37771579, 2023). "CX3CL1, as a prognosis indicator, promoted tumour cell migration, invasion and ICAM‐1 expression by activating CX3CR1/PLCβ/PKCα/c‐Src/c‐Jun/AP‐1 pathway." (PMID 37082943, 2023). "As indicated by the ROC analyses, CX3CL1 was able to identify tumor tissues from normal tissues in these cancers with significant changes in CX3CL1 expression." (PMID 37153002, 2023). "This axis of CX3CR1 with its ligand Fractalkine CX3CL1 is suggested to play an ambiguous role in oncogenesis since it can exercise pro- and anti-tumor functions." (PMID 36900266, 2023). "Thereby, the effect of CX3CL1 on tumor progression is completely different in different stages of BC." (PMID 36794651, 2023). "Of these tumor size-associated cytokines, seven (TNF-β, MCP-3/CCL7, Fractalkine/CX3CL1, GRO/CXCL1, sCD40L, TGF-α, and MDC/ADAM11) were among those newly investigated as part of a bead array-based vitreous cytokine analysis of UM." (PMID 37509362, 2023). "Although, CX3CL1 additionally has tumor-suppressive activity as CX3CL1 overexpression has been shown to increase the chemotactic efficiency and infiltration of immune effector cell, resulting in an improved prognosis." (PMID 37770496, 2023). "The CX3CR1 ligand, CX3CL1, has been shown to be expressed on tumor cells and facilitates their migration." (PMID 37771579, 2023). "In breast cancer and testicular germinal tumor, CX3CL1 mediates the infiltration of TAMs, resulting in poor tumor prognosis, but the specific types of TAMs are unclear and further research is needed." (PMID 36173487, 2023). "BRCA, KICH, KIRC, and LUAD were the tumor types with significant differential expression of CX3CL1 in both databases." (PMID 37153002, 2023). "Results of IHC staining for levels of CX3CL1 in patients were with a higher‐grade OSCC than in those with a lower‐grade OSCC; the level of CX3CL1 expression was reflected by the tumour stage." (PMID 37082943, 2023). "iFGFR1‐induced CX3CL1 enhanced the migration of macrophages during the initial stage of tumor formation and blocking CX3CR1 significantly decreased the recruitment of macrophages in MMTV‐iFGFR1 mice." (PMID 36794651, 2023). "Among the 19 cancer types with significant differential expression, those with higher CX3CL1 expression in tumor tissues than in normal tissues were categorized as upregulated, while those with lower expression were categorized as downregulated." (PMID 37153002, 2023). "Using a Boyden chamber-based migration assay, we found that CT26 tumor cells pre-treated with CX3CR1 mAb had reduced migration towards a CX3CL1 gradient." (PMID 37771579, 2023). "Nevertheless, the investigation of the stimulatory effects of CX3CL1 on the tumour cell motility and progression in OSCC cells at signalling mechanism and gene expression levels was limited." (PMID 37082943, 2023). "We treated CT26 tumor cells with CX3CL1 and determined which soluble mediators were upregulated in the tumor cells by mRNA and multiplex ELISA analysis." (PMID 37771579, 2023).